BRCA1 (BRCA1 DNA repair associated)
Diseases named in the same sentence as BRCA1 in open-access papers (continued):
Sharing a sentence is not in itself a finding about the gene and the disease.
ovarian carcinoma (continued). "In particular, PARPi’s have been approved as maintenance therapy for ovarian cancer patients with a germline or somatic BRCA1/2 mutation after completion of adjuvant treatment." (PMID 34686201, 2021). "Ovarian cancer cells often carry BRCA1 or BRCA2 (BRCA1/2), germline or somatic mutations in ataxia telangiectasia and Rad3-related protein (ATR) or checkpoint kinase 1 (CHK1) genes of the homologous recombination (HR) pathway." (PMID 34072593, 2021). "Given the poor prognosis associated with this disease, identifying PVs in genes that confer an increased risk for ovarian cancer outside of BRCA1 and BRCA2 is critical for appropriate patient management." (PMID 33926482, 2021). "More than 80% of BRCA1/2 mutation carriers develop breast and/or ovarian cancer during their lifetime." (PMID 34805171, 2021). "The risk of ovarian cancer increases significantly by the age of 36–39 with BRCA1 mutation carriers and by the age of 44–46 with BRCA2 mutation carriers." (PMID 34828379, 2021). "Real-time PCR and immunohistochemical analysis showed that the levels of AT1R decrease in BRCA1-mutated ovarian cancer." (PMID 35008474, 2021). "Patients with pathogenic sequence variants (PSVs) in BRCA1/BRCA2 are at high risk of developing ovarian cancer (OC)." (PMID 34930165, 2021). "Although germline mutations in BRCA1 highly predispose women towards breast and ovarian cancer, few substantial improvements in preventing or treating such cancers have been made." (PMID 33767581, 2021). "In recent years, inhibitors of poly(ADP-ribose) polymerase (PARP) have emerged as a promising new therapeutic approach for ovarian cancer treatment, especially for high-grade ovarian carcinoma with mutations in the BRCA1 or BRCA2 tumor suppressor genes." (PMID 34956861, 2021). "Olaparib has already been shown to be useful for maintenance treatment after platinum-based chemotherapy of ovarian cancer harboring germline/somatic BRCA1/2 mutations." (PMID 34209310, 2021). "One of 9 mutations in BRCA1 was detected in 220 out of 2095 (10.5%) ovarian cancer cases and in 5 out of 1743 controls (0.29%), and was associated with odds ratio 40.8 (95% CI: 18.7–114.8; p = 0.29 × 10−15)." (PMID 33670479, 2021). "BRCA1 has been widely recognized for conferring increased susceptibility for breast and ovarian cancer in individuals carrying a mutation in the gene." (PMID 34222870, 2021). "Then, rucaparib was approved in 2016 for the treatment of advanced ovarian cancer with both germline and somatic mutations in BRCA1/2 genes." (PMID 34671561, 2021). "We report a significant splicing variant (c.5074+3A>C) in BRCA1 in a patient with recurrent ovarian cancer." (PMID 34073420, 2021). "Breast cancer susceptibility gene 1 (BRCA1) encodes the tumor suppressor BRCA1, which was first linked to hereditary breast and ovarian cancer in the early 1990s." (PMID 35008272, 2021). "First, the Abcb1a and Abcb1b genes, members of the ATP‐binding cassette, encoding the multidrug resistance protein (MDR1 or P‐gp) involved in resistance of BRCA1/2‐deficient breast and ovarian cancer patients to PARP inhibitors, are upregulated." (PMID 34761497, 2021). "Here, we generate induced pluripotent stem cells (iPSCs) from healthy individuals and young ovarian cancer patients with germline pathogenic BRCA1 mutations (BRCA1mut)." (PMID 34965417, 2021). "This study also demonstrated that BRCA1 deficiency in ovarian cancer is associated with changes in the expression of several cytoskeleton and cell adhesion regulatory proteins." (PMID 35008272, 2021). "To determine the performance of ASHRA as a quantitative assay, we measured the HR activity of the BRCA1-R1699Q and -V1736A pathogenic variants, which are associated with an intermediate risk of breast and ovarian cancer." (PMID 36860287, 2021). "The risk of developing ovarian cancer varies between 39%-63% and 16.5%-27% in women with pathogenic mutations in the BRCA1 and BRCA2, respectively." (PMID 34547799, 2021).
ovarian carcinoma (continued). "The findings support early RRBSO ideally just before the main risk periods for ovarian cancer in BRCA1 aged 35 years (there were two ovarian cancers aged 37.7 and 38.7 years) and BRCA2 aged 45 years." (PMID 33152107, 2021). "The low frequency of OS tumors truly deficient in BRCA1/2, in contrast to breast and ovarian cancers, implies that the increased presence of BRCAness in OS arises from alterations in other genes of the HR pathway, each of which contributes to HRD." (PMID 34762643, 2021). "Inhibition of RAD52 (RAD52 Homolog, DNA Repair Protein), the master regulator of SSA, results in decreased proliferation of BRCA1/2 (BRCA1/2 DNA Repair Associated)-deficient cells, occurring in many hereditary breast and ovarian cancer cases." (PMID 33671579, 2021). "Alterations of BRCA1/2 are found in more than 50% of HR-deficient ovarian cancers, whereas alterations of non-BRCA1/2 HR factors, including RAD51C or PALB2, are present in the remaining cases." (PMID 36860287, 2021). "Ovarian cancer is known to be associated with germline alterations in BRCA1 or BRCA2, though somatic mutations can also occur." (PMID 34198738, 2021). "PARP inhibitors have recently been approved to treat the advanced ovarian cancer patients with BRCA1/2 mutations." (PMID 34257528, 2021). "Approximately, 10–15% of epithelial ovarian cancer (EOC) patients carry germline mutation in BRCA1 or BRCA2., and it was particularly high in high grade serous subtype, which was reported at about 20–30%." (PMID 33773534, 2021). "A phase 2 clinical trial (NCT02734004) of olaparib and programmed cell death ligand 1 (PDL-1) inhibitor durvalumab (Imfinzi) in platinum-sensitive relapsed germline BRCA1/2-mutated ovarian cancer is an example." (PMID 33803939, 2021). "Epithelial ovarian cancers are associated with a moderately strong genetic susceptibility, with heterozygous carriers of BRCA1 and BRCA2 germline mutations having increased lifetime risk of developing ovarian cancer of 40–60% and 11–30%, respectively." (PMID 34070674, 2021). "Among those, olaparib was firstly approved as the maintenance therapy in 2014, particularly for platinum-sensitive advanced ovarian cancer with germline mutations in BRCA1/2 genes that are involved in the HR pathway of DNA double-strand break (DSB) repair." (PMID 34671561, 2021). "The pathogenic mutation BRCA1 Asp1362fs was found in 1 BC patient, 1 ovarian cancer patient, and 2 healthy family members." (PMID 34570441, 2021). "Overall, this study demonstrates considerable variation in transcriptomic landscapes of breast and ovarian cancers associated with the affected gene (BRCA1 vs. BRCA2), as well as the mutation type (somatic vs. germline)." (PMID 33525353, 2021). "Simultaneous BRCA1/2 pathogenic variants were also identified in a systematic review of women with epithelial ovarian cancer." (PMID 33507482, 2021). "Lastly, based on its mutation and dysregulated expression, the BRCA1 gene is one of the most important genes for the susceptibility of breast and ovarian cancers, and its clinical application in cancer diagnosis has been reported." (PMID 34926299, 2021). "A BRCA1 or BRCA2 gene mutation was detected in 54 of the 214 (25.2%) women affected with epithelial ovarian cancer." (PMID 33478551, 2021). "The pathogenic genetic variant also predisposes women to a cumulative risk for ovarian cancer up to 44% in BRCA1, and 17% in BRCA2 mutation carriers." (PMID 34069035, 2021). "The prevalence and association of the founder mutations with ovarian cancer risk in the Polish population was limited to analysis of BRCA1/2 in relatively small groups of cases, and was not performed for other genes." (PMID 33670479, 2021). "We illustrate another feature of our framework by analyzing a list of hit genes nominated by a bespoke CRISPR drug screen for gene essentiality in BRCA1-wild type and BRCA1-mutated breast and ovarian cancer." (PMID 34663427, 2021).
ovarian carcinoma (continued). "In contrast, in the ovarian cancer dataset, most of the deregulations in functional gene sets were associated with somatic BRCA1 and germline BRCA2 mutations." (PMID 33525353, 2021). "In ovarian carcinoma patients, more frequently, BRCA1 mutations, but also BRCA2 germline mutations are detected in 18 to 23% of cases." (PMID 34944094, 2021). "It has been shown that ovarian cancer patients from Belarus are characterized by a high proportion of a limited number of recurrent mutations in the BRCA1 gene." (PMID 33478551, 2021). "The prevalence of germline and somatic BRCA1/2 mutations are highest in breast and ovarian cancers and their presence is associated with an indication for PARP-inhibitor therapy." (PMID 33525353, 2021). "Of the 21 study participants with ovarian cancer, 5 had a P/LP variant in BRCA1 (n = 4) and BRCA2 (n = 1) and were diagnosed with high-grade papillary serous ovarian cancer." (PMID 33646313, 2021). "The direct regulation of BRCA1, variations in which are linked to increased risks of breast and ovarian cancers, by ELK1/c-Fos/Jun has also been documented." (PMID 34966781, 2021). "The genes BRCA1 e BRCA2 are the strongest recognized genetic risk factors for epithelial ovarian cancer, although some studies show an association with the AXIN2 gene in several cancers, including the ovarian one." (PMID 34378652, 2021). "For instance, the proband in this case was counseled on breast and ovarian cancer risk based on the presence of a known BRCA1 variant." (PMID 33507482, 2021). "In fact, in the general population’s lifetime, the risk of developing breast and ovarian cancer is 12 and 1.5%, respectively, while for a woman carrying a PV of the BRCA1 gene, the risk grows to 67 and 40%, respectively." (PMID 34572941, 2021). "Female carriers of BRCA1/BRCA2 variants also have the additional high risk of ovarian cancer, with the cumulative lifetime risk in carriers of BRCA1 being 44% (36–53%), compared to BRCA2, which is 17% (11–25%)." (PMID 34771713, 2021). "Because of the high susceptibility of BRCA1 to ovarian cancer, for molecular and genetic tests of ovarian cancer, BRCA1 is one of the most indispensable genes for probing." (PMID 33937409, 2021). "The authors found that the presence of ovarian cancer and known risk factors including BRCA1 mutation and older age were significantly associated with non-Lactobacillus dominant cervicovaginal microbiomes." (PMID 34208337, 2021). "Accordingly, the cumulative risk of ovarian cancer until the age of 70 was 39-40% in patients with BRCA1 mutation, and this risk was reported as a mean of 11-70% in patients with BRCA2 mutation." (PMID 34629107, 2021). "Taken together, these results indicate significant variability of transcriptomic programs in breast and ovarian cancers associated with germline and somatic mutations in BRCA1 and BRCA2 genes." (PMID 33525353, 2021). "We found only one case of MMR proficient LS-associated ovarian cancer, in a woman who also carried a BRCA1 pathogenic variant and whose tumour is likely to have developed via a non MMR driven pathway." (PMID 32917768, 2021). "Especially as Poly (ADP-ribose) polymerase inhibitors have shown clinical benefit for treatment of breast or ovarian cancer with the presence of a BRCA1 or BRCA2 pathogenic variant, identifying these variants is more important than ever." (PMID 34063308, 2021). "Individuals with BRCA1 mutations not only have a substantial increased risk for breast and ovarian cancer, but an increased risk for other cancers, such as pancreatic and cervical cancer as well." (PMID 34222870, 2021). "BRCA1/2-associated hereditary breast and ovarian cancer is the most common form of hereditary breast and ovarian cancer and occurs in all ethnicities and racial populations." (PMID 34572941, 2021). "In a phase I clinical trial, one particular ATRi, VX-970, showed efficacy in patients with BRCA1-mutated ovarian cancer that was platinum refractory and PARPi resistant." (PMID 34070674, 2021).
ovarian carcinoma (continued). "We found that decreased expression of BECN1 and BRCA1 in ovarian cancers was significantly associated with high DNA methylation of these genes." (PMID 33670664, 2021). "Secondary epimutations have also been evaluated in breast and ovarian cancer, where people who carry germline BRCA1 and BRCA2 mutations are at high risk of developing this syndrome." (PMID 34638292, 2021). "BRCA2 and BRCA1 PTVs were associated with an increased burden of small somatic deletions, tandem duplications, and templated insertions in breast and ovarian cancers as well as other tumors like adenocarcinomas of the prostate and pancreas." (PMID 34097189, 2021). "Another clinical trial is aimed at targeting ATM deficient advanced lung adenocarcinomas as well as high grade ovarian cancers that harbor BRCA1/2 mutations using a combination of AZD6738 and carboplatin (NCT02264678)." (PMID 33498525, 2021). "Women with PVs in BRCA1 or BRCA2 have a cumulative lifetime risk of ovarian cancer of 44% to 61% and 17% to 24%, respectively." (PMID 33152107, 2021). "The meta-analyses showed that the risk of developing ovarian cancer in patients with BRCA1 mutation was cumulatively higher." (PMID 34629107, 2021). "In contrast, women carrying a BRCA1 or BRCA2 pathogenic variant would consider delaying oophorectomy if found to have low ovarian cancer PRS assessment, as delaying the onset of surgically induced menopause was appealing." (PMID 34683136, 2021). "In ovarian cancer, BRCA1/2-mutated tumors with a higher level of neoantigens than those without alterations in HR genes and BRCA1/2 defects are associated with an increase of PD-L1 expression and T-cell infiltration." (PMID 34712221, 2021). "The results demonstrate that the PRS developed using population-based data are also associated with breast and ovarian cancer risk for women with BRCA1/2 pathogenic variants." (PMID 32665703, 2020). "LOH, TAIs, and LSTs were shown to correlate well with mutations in HR genes BRCA1/2 in breast and ovarian cancer." (PMID 32029455, 2020). "For example, PARP inhibitor olaparib showed a 70% reduction in the risk of progression or death for ovarian cancer patients with BRCA1/2 mutation." (PMID 32860347, 2020). "The cumulative risk to the age of 80 years for ovarian cancer is elevated up to 44% in BRCA1 and up to 17% in BRCA2 mutation carriers." (PMID 32719921, 2020). "It was reported that 8.9% and 3.0% of ovarian cancer have BRCA1 and BRCA2 somatic variants, respectively." (PMID 32813918, 2020). "Early studies of cases selected for a family history of breast or ovarian cancer found that 24–76% had deleterious variants in BRCA1 and 1–17% had deleterious variants in BRCA2." (PMID 33086730, 2020). "Deficiency of BRCA1 function is associated with breast and ovarian cancer as well as other types of cancer." (PMID 31963223, 2020). "The last BRCA1 pathogenic variant we found in this study is c.5158C > T (p.Arg1720Trp), it was detected in a patient with ovarian cancer." (PMID 32778078, 2020). "HBOC, an inherited disorder that predisposes to a substantial lifetime risk of breast and ovarian cancers, is mostly attributed to pathogenic variants in either breast cancer gene 1 or breast cancer gene 2 (BRCA1 and BRCA2, respectively)." (PMID 32708810, 2020). "Women carrying mutations in these genes have a lifetime risk of developing ovarian cancer of 36 to 60% for BRCA1 and 16 to 27% for BRCA2." (PMID 32316968, 2020). "The most well-known example of a successful synthetic lethality approach is the case of PARP inhibitors as ovarian cancer treatment, particularly in the case of BRCA1/2 deficient cells, which are defective in both HR and ICL repair." (PMID 36046263, 2020). "From 2004, the Department of Genetics of National Institute of Oncology, Budapest, Hungary, has been involved in the BRCA1/2 germline mutation screening of the enrolled high-risk Hungarian breast and ovarian cancer patients." (PMID 32629901, 2020).
ovarian carcinoma (continued). "BRCA1/2 mutation is a marker of hereditary breast and ovarian cancers and is related to improved survival among patients 41-44." (PMID 33033501, 2020). "A genetic predisposition is thought to account for 5 to 10% of ovarian cancers, mainly through alterations of the BRCA1 gene, and more rarely, the BRCA2 gene." (PMID 32650744, 2020). "We found 8 mutations in the BRCA1 gene of the selected HOCS family of ovarian cancer patients (6 located in exon 11)." (PMID 32356124, 2020). "Identification of germline and somatic BRCA1/2 mutations in ovarian cancer is important for genetic counseling and treatment decision making with poly ADP ribose polymerase inhibitors." (PMID 32856862, 2020). "The introduction of PARPi in clinical practice for the treatment of patients with advanced ovarian cancer imposed changes in the molecular diagnosis of BRCA1/BRCA2 variants." (PMID 32850417, 2020). "We tested the association of RAD52 S346X with risk of developing breast or ovarian cancer in a large cohort of BRCA1 and BRCA2 mutation carriers." (PMID 32175645, 2020). "The most significant risk factors for ovarian cancer are inherited genetic mutations of BRCA1 or BRCA2 genes that are responsible for about 10 to 15 percent of all ovarian cancers." (PMID 32823855, 2020). "We investigated the association of the RAD52 S346X variant as a modifier of the risk of developing breast and ovarian cancers in BRCA1 and BRCA2 mutation carriers from the Consortium of Investigators of Modifiers of BRCA1/2." (PMID 32175645, 2020). "Deleterious mutations on BRCA1/2 genes are known to confer high risk of developing breast and ovarian cancers." (PMID 33240314, 2020). "Germline mutations in BRCA1 confer a cumulative breast and ovarian cancer risk by age 80 of 72% and 44%, respectively, while BRCA2 mutations confer a 69% and 17% increased risk of breast and ovarian cancer by this age, respectively." (PMID 32455662, 2020). "For BRCA1 mutation carriers, there is a predominant predisposition of breast and ovarian cancer, while BRCA2 mutation carriers also show a significantly higher risk of pancreatic, prostate, and other types of cancers in addition to breast and ovarian cancers." (PMID 33299637, 2020). "The cumulative risk of ovarian cancer in the BRCA1 and BRCA2 mutation carriers was 40% and 18%, respectively, at age 70, which was much higher than 1.4% in the general population." (PMID 32356124, 2020). "NGS-based somatic mutation analysis, as well as germline BRCA1/2 mutation analysis, should become the standard of care for managing women with ovarian cancer to widen the indication of PARP inhibitors." (PMID 32164585, 2020). "In this review, we analyse the published data on OC and risk for breast or ovarian cancer in BRCA1/2 mutation carriers." (PMID 32140806, 2020). "Secondary reverse mutations in BRCA1/2 were also shown to correlate with PARPi resistance in ovarian cancer and other cancers." (PMID 32833070, 2020). "As it has been reported in breast and ovarian cancers, mutation in BRCA1/2 is correlates with early development of cancer, which are responsive to genotoxic anti-cancer therapies." (PMID 33198792, 2020). "In the SOLO-1 trial, olaparib was tested as a frontline maintenance treatment in women with newly diagnosed FIGO stage III–IV ovarian cancer with germline or somatic BRCA1/2 mutation following cytoreductive surgery and platinum-based chemotherapy." (PMID 33036656, 2020). "Initial preclinical study conducted on an immunocompetent BRCA1-deficient BR5 murine ovarian cancer model revealed that anti-CTLA-4 combined with PARPi veliparib enhanced IFN-γ production and effector/memory T cell infiltration." (PMID 32526888, 2020). "Of patients with ovarian cancer, 14.5–24% carried germ-line mutations in cancer-associated genes, including BRCA1/2 mutations that were observed in 13.3–15.3%." (PMID 32098383, 2020).